PRSS8 (serine protease 8)
Description:
Possesses a trypsin-like cleavage specificity with a preference for poly-basic substrates. Stimulates epithelial sodium channel (ENaC) activity through activating cleavage of the gamma subunits (SCNN1G).
Synonyms: CAP1; PROSTASIN
Tractability: Small molecule: a structure with a bound ligand is known; a high-quality ligand is known; it has a binding pocket of medium quality. Antibody: its Gene Ontology location is reachable by antibodies, with high confidence; UniProt places it where antibodies can reach, with medium confidence; UniProt predicts a signal peptide or a membrane-spanning region. PROTAC: its protein half-life has been measured; a small molecule that binds it is known.
Target class: Serine protease; Enzyme; Serine protease PA clan; Serine protease S1A subfamily; Protease
Gene: Protein-coding gene on chromosome 16 (31,131,433 to 31,135,727, reverse strand). Ensembl gene ENSG00000052344.
Subcellular location: Cell membrane (Prostasin); Secreted, extracellular space (Prostasin light chain); Secreted, extracellular space (Prostasin heavy chain)
Pathways (Reactome):
Developmental Biology: Formation of the cornified envelope
Gene Ontology:
Molecular function: protein binding; serine-type peptidase activity; serine-type endopeptidase activity
Biological process: positive regulation of sodium ion transport; protein processing; proteolysis
Cellular component: extracellular exosome; extracellular region; plasma membrane
Genetic constraint (gnomAD): Loss-of-function variants: 14 observed, 27.73 expected, observed/expected ratio (o/e) 0.5, 90% interval 0.33 to 0.79. The upper end of that interval is the gene's LOEUF score, 0.79, which puts it in group 3 of 6, group 1 being the genes least tolerant of losing a copy. Missense variants: 362 observed, 449.38 expected, observed/expected ratio (o/e) 0.81, 90% interval 0.74 to 0.88. Synonymous variants: 183 observed, 189.16 expected, observed/expected ratio (o/e) 0.97, 90% interval 0.86 to 1.09.
Homologues: Orthologues: chimpanzee PRSS8 (97% identical), dog PRSS8 (80% identical), mouse Prss8 (76% identical), rabbit PRSS8 (76% identical), rat Prss8 (75% identical), pig PRSS8 (74% identical), guinea pig PRSS8 (72% identical), tropical clawed frog prss8 (41% identical).
Diseases named in the same sentence as PRSS8 in open-access papers:
PRSS8 is named in the same sentence as 53 diseases in open-access papers, as found by Europe PMC text mining. Sharing a sentence is not in itself a finding about the gene and the disease. The quoted sentences say what the papers report.
ovarian carcinoma (11 papers, 2012 to 2025). A malignant neoplasm originating from the surface ovarian epithelium. "Recent western blot analysis of sera that had been depleted of the highly abundant proteins showed that PRSS8 levels were increased in early stage ovarian cancer samples compared to benign samples or healthy controls." (PMID 29051715, 2017). "Previous studies have demonstrated that PRSS8 was differentially expressed in ovarian cancer, prostate cancer and breast cancer." (PMID 27050145, 2016). "The levels of PRSS8 in ovarian carcinoma cell lines are elevated, and the protein level is increased in the serum of late stage OVC patients." (PMID 27036110, 2016). "PRSS8 is also overexpressed in ovarian cancer and may contribute to tumor progression and EMT, with its prognostic value possibly varying by cancer subtype; it is considered a potential biomarker for early detection and disease monitoring." (PMID 41465326, 2025). "In addition to the well-known ovarian cancer serum biomarkers CA125 and HE4, we identified six additional proteins, MK, hK11, KLK6, FRα, PRSS8, and IL-6, that had previously been reported as serum biomarkers for ovarian cancer." (PMID 29051715, 2017). "Interestingly, recent studies have reported that serum PRSS8 level is increased in ovarian cancer patients, but PRSS8 expression was decreased in chemoresistant ovarian cancer patients and chemoresistant cell line." (PMID 27081034, 2016). "Additionally, the differential expression of PRSS8 has been identified in prostate, breast, gastric and ovarian cancer cases, and the downregulation of PRSS8 in these cases of epithelial cancer was attributed to DNA hypermethylation." (PMID 25351113, 2015). "Moreover, increased expression of PRSS8 induced cells death in ovarian cancer cell lines." (PMID 27081034, 2016). "Ongoing research continues to investigate new promising biomarkers for the early detection of ovarian cancer, such as KLK6/7, GSTT1, PRSS8, FOLR1, and ALDH1." (PMID 26779384, 2015). "Promising biomarkers for early detection of ovarian cancer include KLK6/7, GSTT1, PRSS8, FOLR1, ALDH1, and miRNAs." (PMID 23319948, 2012). "The same study also confirmed downregulation of PRSS8 after silencing ZNF217 expression indicating the significance of ZNF217 as a key regulator and suggesting PRSS8 as a potential biomarker in ovarian carcinomas." (PMID 23319948, 2012). "Prostasin (PRSS8), GSTT1, FOLR1, KLK6, KLK7, and ALDH1 are all currently under research and clinical trials and are also potential biomarkers for early detection of ovarian cancer." (PMID 23319948, 2012).
colorectal cancer (6 papers, 2016 to 2025). A primary or metastatic malignant neoplasm that affects the colon or rectum. "We found that PRSS8 expression was significantly reduced in colorectal cancers, and the decreased expression of PRSS8 was associated with clinical stages, poor differentiation, and poor outcomes." (PMID 28991193, 2017). "In the present study, we identified that PRSS8 expression was reduced in colorectal cancer and this reduced expression was associated with poor differentiation and late stages of tumors, and with poor outcome of colorectal cancer patients." (PMID 27050145, 2016). "Mechanistic studies revealed that PRSS8 inhibited Sphk1/S1P/Stat3/Akt signaling pathway, in terms of inverse association between PRSS8 and Sphk1 in human colorectal cancers and in Sphk1-/− mice." (PMID 27050145, 2016). "Most importantly, the reduced expression of PRSS8 was associated with shorter survival time in patients with colorectal cancers." (PMID 27050145, 2016). "PRSS8 was typically regarded as a tumor suppressor in some cancer types including hepatocellular carcinoma and colorectal cancer." (PMID 34905506, 2021). "Mechanistically, PRSS8 negatively correlated with Sphk1 in both a Sphk1 knockout mouse model and human colorectal cancers." (PMID 28991193, 2017). "It is strongly suggested that PRSS8 is a tumor suppressor and has important clinical significance in colorectal cancer." (PMID 27050145, 2016). "Due to the strong correlation between PRSS8 expression levels and clinical significance, we then used gain- and loss-of-expression approaches to determine the biological functions of PRSS8 in colorectal cancer in vitro and in nude mice." (PMID 27050145, 2016). "Four human colorectal cancer cell lines were screened for PRSS8 mRNA and protein levels by qRT-PCR and immunoblotting, respectively." (PMID 27050145, 2016). "The results generated from these experiments strongly suggested that PRSS8 is a tumor suppressor in colorectal cancer, which is through inhibiting Sphk1/S1P/Stat3 signaling pathways." (PMID 27050145, 2016). "Similar to colorectal cancer, PRSS8 expression levels were reduced in esophageal cancers and liver cancers compared to normal adjacent tissues." (PMID 27050145, 2016). "Besides, PRSS8 is a tumor suppressor that has been shown to have essential roles in the prevention of colorectal cancer development and metastasis." (PMID 35571488, 2022). "For example, PRSS8 can inhibit the carcinogenesis and metastasis of colorectal cancer." (PMID 34823420, 2021). "However, enforced expression of PRSS8 led to the inhibition of colorectal cancer cell proliferation and retarded cancer cell growth in nude mice." (PMID 28991193, 2017). "Furthermore, increase of PRSS8 led to the inhibition of colorectal cancer cell proliferation, knockdown of PRSS8 accelerated cell proliferation in vitro, and overexpressing PRSS8 retarded cancer cell growth in nude mice." (PMID 27050145, 2016). "To determine whether PRSS8 protein levels in colorectal cancers were also reduced, we conducted immunohistochemical staining in a colorectal cancer tissue microarray (TMA) that contained 282 cases of colorectal cancer with follow-up information." (PMID 27050145, 2016). "Interestingly, in normal colonic mucosa, PRSS8 expression was higher and Sphk1 was lower, but, in colorectal cancer tissues, PRSS8 expression was decreased and Sphk1 expression was increased, showing an inverse correlation." (PMID 27050145, 2016). "In conclusion, we have identified PRSS8 as a tumor suppressor in colorectal cancer formation and progression, and PRSS8 might be one of the key elements that suppress Sphk1/S1p/Stat3/Akt inflammatory signaling during colorectal carcinogenesis." (PMID 27050145, 2016). "The decrease of PRSS8 during carcinogenesis could be resulted from promoter hypermethylation, and the increase of Sphk1 could be activated by upstream signaling (e.g. inflammatory signaling) during colorectal cancer initiation and progression." (PMID 27050145, 2016).
colorectal cancer (continued). "Mechanistically, PRSS8 has been shown to inhibit the Wnt/β-catenin, EMT, and cancer stemness pathways, particularly in colorectal cancer." (PMID 40723891, 2025). "To determine how PRSS8 expression differed between normal and tumor colorectal tissues, we used qRT-PCR to measure PRSS8 mRNA levels in 38 pairs of colorectal cancer tissues and their adjacent non-cancer tissues." (PMID 27050145, 2016). "Compared to the adjacent non-cancer tissues, colorectal cancers showed significant reduction of PRSS8 expression." (PMID 27050145, 2016). "We found that PRSS8 inhibited Sphk1/S1P/Stat3 signaling, in terms of negative correlation of PRSS8 and Sphk1 in vitro, in Sphk1 mouse model and in human colorectal cancers." (PMID 27050145, 2016). "To determine the effects of knockdown of PRSS8 expression in colorectal cancer cells, we decreased expression of PRSS8 of the high-expression colorectal cancer cell lines Caco2 and HCT8 using small interfering RNA (siRNA) targeting human PRSS8 (siR-PRSS8)." (PMID 27050145, 2016). "While it has been studied extensively in other cancers, the effect of PRSS8 on colorectal cancer is not clear." (PMID 27050145, 2016).
prostate carcinoma (6 papers, 2013 to 2023). A carcinoma that arises from epithelial cells of the prostate gland. "PRSS8 encodes for prostasin, a member of the trypsin family of serine proteases that has been implicated in inhibition of metastasis of both breast and prostate cancer cells." (PMID 25753662, 2015). "We have shown previously that hypermethylation at some of these sites (CpG-3 and CpG-5) is causative to PRSS8 expression down-regulation in human bladder, breast, and prostate cancer cell lines." (PMID 23724145, 2013). "In prostate cancer, reduced PRSS8 was associated with hypermethylation of PRSS8." (PMID 27081034, 2016). "Consistent with previous studies, PRSS8 expression was reduced in breast and prostate cancers, compared to breast and prostate adenomas." (PMID 27050145, 2016). "Human CAP1/Prss8 has been previously isolated from seminal fluids of prostate cancer patients and named prostasin." (PMID 23405214, 2013). "Noteworthy is the identification, by us and other researchers, of tumor-suppressing proteins like serine protease 8 (PRSS8) and nidogen 1 (NID1) within the urine of prostate cancer patients." (PMID 38250812, 2023).
Insulin resistance (5 papers, 2014 to 2023). Increased resistance towards insulin, that is, diminished effectiveness of insulin in reducing blood glucose levels. "Liver-specific PRSS8 knockout (LKO) mice develop insulin resistance associated with the increase in hepatic TLR4." (PMID 24614850, 2014). "In the cited former study using the LKO mice fed HFD, liver-specific ablation of PRSS8 promoted insulin resistance driven by presence of a HFD." (PMID 34361079, 2021). "To ensure that the reduction in hepatic PRSS8 is responsible for the insulin resistance phenotype, we generated liver-specific PRSS8 knockout (LKO) mice." (PMID 24614850, 2014). "Forced expression of human PRSS8 or TLR4 depletion in db/db mouse livers ameliorated the insulin resistance." (PMID 24614850, 2014). "In addition, we found that HFD triggers the downregulation of PRSS8 via augmentation of ER stress in the liver, thereby contributing to the development of hepatic insulin resistance and diabetes." (PMID 24614850, 2014). "Previous studies have shown that liver-specific knockout of PRSS8 reduced the phosphorylation of AKT in the liver, resulting in insulin resistance." (PMID 34966805, 2021). "Restoration of PRSS8 expression in livers of HFD, LKO and db/db mice decreases the TLR4 level and ameliorates insulin resistance." (PMID 24614850, 2014). "In this study, we demonstrate that the serine protease prostasin (PRSS8) protects the liver from chronic inflammation via the proteolytic cleavage and shedding of TLR4, consequently preventing the liver from developing insulin resistance." (PMID 24614850, 2014). "Moreover, restoring PRSS8 hepatic synthesis of the LKO mice decreased TLR4 expression and ameliorated insulin resistance with the HFD." (PMID 34361079, 2021). "Knockdown of myeloid differentiation primary response gene 88 (MYD88), an adaptor protein for TLR4, improved the insulin resistance in LKO mice, and overexpression of PRSS8 in the liver did not decrease blood glucose levels during the GTT and PTT in systemic TLR4 KO mice." (PMID 24614850, 2014).
hepatocellular carcinoma (4 papers, 2017 to 2024). A malignant tumor that arises from hepatocytes. "The serine protease enzyme (PRSS8) has exhibited anti-tumorigenic effects in bladder, breast, colorectal, and hepatocellular cancer." (PMID 38335839, 2024). "PRSS8 down-regulated and inhibited the growth and metastasis of hepatocellular carcinoma cells." (PMID 34823420, 2021).
breast carcinoma (3 papers, 2015 to 2021). "The present study employed tissue microarrays of colorectal, esophageal and liver cancers as well as prostate and breast cancers, to investigate the expression of PRSS8 and its clinical significance in these cancers." (PMID 27050145, 2016). "Mutating these residues abrogates interaction of MBD2 with the histone deacetylase core and impairs the ability of MBD2 to repress the methylated tumor suppressor gene PRSS8 in MDA-MB-435 breast cancer cells." (PMID 25753662, 2015). "In this study, using five sets of variant TMAs, including colorectal, esophageal, liver, prostate, and breast cancers, we have found that PRSS8 expression was reduced in all of the five types of cancer tissues, and poorly differentiated cancers exhibited less or absent expression of PRSS8." (PMID 27050145, 2016). "To test this hypothesis, we assayed the expression of a previously identified highly methylated MBD2 target gene, PRSS8, in MDA-MB-435 breast cancer cells." (PMID 25753662, 2015).
colon carcinoma (3 papers, 2022 to 2024). "Thus, LINC00893, miR-146b-3p, and PRSS8 genes might take part in colon cancer pathogenesis, providing novel diagnostic biomarkers of colon cancer." (PMID 35571488, 2022). "The results showed that PRSS8 protein expression was downregulated in colon cancer tissues (P < 0.01)." (PMID 35571488, 2022). "Present study has revealed the up-regulated expression of miR-146b-3p in colon cancer and its downregulation on PRSS8." (PMID 35571488, 2022). "Current study has shown the expression of LINC00893, miR-146b-3p, and PRSS8 in colon cancer tissue samples (n = 30) and adjacent tissues (n = 30) by RT-qPCR." (PMID 35571488, 2022). "Further, silenced PRSS8 reversed the inhibition induced by miR-146b-3p knockdown on cell proliferation in colon cancer cells, as revealed by EdU assay (P < 0.05)." (PMID 35571488, 2022). "LINC00893 and PRSS8 were significantly downregulated, while miR-146b-3p was upregulated in colon cancer tissues compared to control group." (PMID 35571488, 2022). "LINC00893 overexpression suppressed the progression of colon cancer by binding with miR-146b-3p to upregulate PRSS8." (PMID 35571488, 2022). "Further, PRSS8 protein expression was measured by western blot in colon cancer and adjacent tissues." (PMID 35571488, 2022). "LINC00893 overexpression can suppress the progression of colon cancer by binding with miR-146b-3p to upregulate PRSS8." (PMID 35571488, 2022). "On the other hand, LINC00893 took part in colon cancer tumorigenesis by binding with miR-146b-3p to upregulate PRSS8." (PMID 35571488, 2022). "We identify multiple genes that are upregulated due to loss of post-transcriptional suppression after inhibition of miR-24-3p, most notably HMOX1 and PRSS8, which are also prominently downregulated in TCGA colon tumors." (PMID 36457077, 2022). "miR-146b-3p expression was found to be negatively correlated with PRSS8 expression in colon cancer tissues (P < 0.001)." (PMID 35571488, 2022). "The results showed that LINC00893 overexpression significantly elevated PRSS8 expression, while miR-146b-3p overexpression significantly reduced the level of PRSS8 in colon cancer cells (P < 0.05)." (PMID 35571488, 2022). "Meanwhile, silenced PRSS8 significantly rescued the promotive effect of miR-146b-3p inhibitors on the apoptosis of colon cancer cells (P < 0.05)." (PMID 35571488, 2022). "Studies had shown that PRSS8 served as a tumor suppressor to regulate colon cancer process." (PMID 39527152, 2024). "LINC00893 and its downstream molecules miR-146b-3p and PRSS8 may serve as novel biomarkers and therapeutic targets of colon cancer, providing new treatment options and research approaches towards colon cancer." (PMID 35571488, 2022). "LINC00893, miR-146b-3p, and PRSS8 may serve as novel biomarkers and therapeutic targets of colon cancer, providing new treatment options and research approaches towards colon cancer." (PMID 35571488, 2022). "PRSS8 knockdown rescued the inhibitory effect of miR-146b-3p knockdown on colon cancer progression." (PMID 35571488, 2022). "Thus, the present study aimed to validate the molecular mechanism of LINC00893 to miR-146b-3p and miR-146b-3p to PRSS8 in colon cancer proliferation, migration, invasion, and apoptosis." (PMID 35571488, 2022). "Moreover, miR-146b-3p overexpression reversed the inhibitory effect of LINC00893, while PRSS8 knockdown rescued the suppressive effect of miR-146b-3p inhibitor on malignant cell behaviors in colon cancer." (PMID 35571488, 2022). "However, the cell cycle arrests in G1 phases were increased miR-146b-3p inhibitor groups of colon cancer cells, while the knockdown of PRSS8 significantly reversed the effect of miR-146b-3p silencing on cell cycle (P < 0.05)." (PMID 35571488, 2022). "Expression of LINC00893, miR-146b-3p, and PRSS8 was detected in colon cancer tissues and adjacent nontumor tissues by RT-qPCR, and clinical significance was analyzed by receiver operating characteristic curve." (PMID 35571488, 2022).
colon carcinoma (continued). "The expression correlation of LINC00893, miR-146b-3p, and PRSS8 in colon cancer tissues (n = 30) was analyzed, and the results showed that LINC00893 expression was negatively correlated with miR-146b-3p expression and positively correlated with PRSS8 expression." (PMID 35571488, 2022).